RET (ret proto-oncogene)
Diseases named in the same sentence as RET in open-access papers (continued):
Sharing a sentence is not in itself a finding about the gene and the disease.
thyroid cancer (continued). "With the dramatic development of molecular diagnostic technologies in recent years, researchers have discovered BRAF, RAS, and telomerase reverse transcriptase (TERT) promoter mutations, RET/PTC rearrangement, and other genetic mutations to be associated with thyroid cancers." (PMID 36133306, 2022). "Pralsetinib potently inhibits the growth of thyroid cancer xenografts driven by various RET mutations and fusions, without inhibiting VEGFR-2." (PMID 35521769, 2022). "Moreover, two novel selective RET inhibitors, selpercatinib and pralsetinib, have been shown to have potent antitumor activity in thyroid cancer with RET alterations." (PMID 36091770, 2022). "In fact, in thyroid cancer, RET signaling has been related to activation of inflammatory programs." (PMID 35044452, 2022). "Similarly, Yoshihara and colleagues found targetable kinase mutations in 4.9% of patients with thyroid cancer and RET fusions, 1% of patients with thyroid cancer with NTRK1 fusions, and 1.8% of patients with thyroid cancer with NTRK3 fusions." (PMID 34981751, 2022). "We sought to determine whether this signature was conserved in human thyroid cancers harboring RET rearrangements." (PMID 35510953, 2022). "This compares to an ORR of 61% and 70% in patients with RET fusion–positive NSCLC who received prior platinum therapy and no prior systemic treatment, respectively, and an ORR of 89% for patients with RET fusion–positive thyroid cancer in previously published data on the ARROW study." (PMID 35962206, 2022). "The aim of the study was to identify patients with NTRK fusion-positive or RET fusion/mutation-positive thyroid cancers, who could benefit from neurotrophic tyrosine kinase receptor (NTRK) or receptor tyrosine kinase (RET) inhibitors." (PMID 34981751, 2022). "We compared WCM271 to RET-rearranged thyroid cancers in the TCGA cohort and the entire cohort." (PMID 35510953, 2022). "Twenty-six of the 29 patients in the safety population enrolled by the 18 October 2021 data cutoff, with RET fusion–positive solid tumors excluding RET fusion–positive NSCLC or thyroid cancer, were enrolled by the efficacy enrollment cutoff date of 18 February 2021." (PMID 35962206, 2022). "Of these, 147 had RET-mutant MTC, and 22 had RET fusion positive thyroid cancers." (PMID 35422765, 2022). "Similarly, pralsetinib also showed an encouraging overall objective response rate (89%, 8 of 9) for patients with RET fusion-positive thyroid cancer." (PMID 36091770, 2022). "Our findings show the need to do studies comparing key mutations in thyroid cancer such as BRAF and RET between Filipinos and other Asian subgroups to see if they may explain differences in clinical characteristics of thyroid cancer." (PMID 36743179, 2022). "PTC is often characterized by RET chromosomal rearrangement, or point mutation of RAS or BRAF proto-oncogenes, all of which are able to trigger the activation of MAPK cascade and therefore the appearance of thyroid carcinoma." (PMID 35453992, 2022). "Activated RET may interact with various kinase proteins to enhance downstream signaling pathways in thyroid cancers." (PMID 34207842, 2021). "Somatic mutations in RAS, PIK3CA, KMT2C, and/or BRAFV600E, as well as somatic RET/PTC rearrangements could act as a somatic “second-hit” in the development of other forms of thyroid cancers in affected individuals." (PMID 33495912, 2021). "An additional predictive molecular target with multi-tumor approved agents are RET alterations, with potentially sensitizing mutations seen in approximately 70% of medullary thyroid cancers (MTC), fusions in <10% of other thyroid cancers and fusions in 1–2% of NSCLC." (PMID 34198738, 2021).
thyroid cancer (continued). "Here, we performed an analysis on the role of FRMD5 in thyroid cancer specimens and cell lines, as we found significant discrepancies in FRMD5 expression between BRAF- and RET-mutated PTCs, as well other types of TCs (TCGA and microarray data analysis of clinical specimens)." (PMID 34201607, 2021). "Besides the present work, TBL1XR1/RET was previously found in one patient from The Cancer Genome Atlas (TCGA) thyroid cancer series." (PMID 34282777, 2021). "It should also be noted that pralsetinib was subsequently approved for RET fusions in advanced NSCLC in September 2020 and advanced, mutated or fusion-positive thyroid cancer patients (similar to the selpercatinib indication) in December 2020 based upon the ARROW trial." (PMID 34198738, 2021). "RET/PTC fusions are involved in the early etiology of thyroid cancer." (PMID 33805984, 2021). "Selpercatinib has been indicated in RET fusion-positive NSCLC as well as thyroid cancers." (PMID 33419162, 2021). "RET-driven thyroid cancers can be efficiently managed by RET inhibitors." (PMID 34681592, 2021). "In May 2020 selpercatinib was approved by the FDA for treatment of RET-mutated MTC, RAI-refractory RET fusion thyroid cancer and RET fusion non-small cell lung cancer." (PMID 34335481, 2021). "Apart from the PI3K/AKT pathway, CNTN1 is also associated with the RhoA pathway in gastric cancer; VEGF-C/VEGFR-3 pathway in lung, gastric, and esophageal cancers, and OSCC; α7 nAChR/ERK and Src-p38 MAPK-C/EBPα pathways in lung cancer; and Notch1 and RET/PTC3 pathways in thyroid cancer." (PMID 33194679, 2020). "Additionally, the selpercatinib LIBRETTO-001 trial has also updated results in RET-fusion thyroid cancer, reaching an ORR of 79% and, again, a DCR of 100%, as well as a median duration of response of 18 months (95% CI: 7.6-NE)." (PMID 32668761, 2020). "Even though NTRK rearrangement is threefold less frequent than RET mutations, a prevalence of TRK fusions has been reported between 5–25% in thyroid cancer and may be seen in DTC, PDTC and ATC." (PMID 32668761, 2020). "In thyroid cancer, the RET proto-oncogene is one of the most common RTKs to be altered." (PMID 32751138, 2020). "RET fusions are uncommon in thyroid cancer subtypes other than PTC." (PMID 32326537, 2020). "RET gene fusions are present in ∼10–20% of PTCs and 6% of poorly differentiated thyroid cancers." (PMID 32292131, 2020). "Findings of a direct correlation between RET/PTC3 and IDO1 and between BRAFV600E and PD-L1 suggest that different driver mutations associated with different subtype of thyroid cancer contribute to different microenvironments and differential recruitment of cells to thyroid tumors." (PMID 33986723, 2020). "Deletion of RET in thyroid carcinomas has been shown to reduce the production of MMP2 and MMP9." (PMID 33020210, 2020). "Point mutations in the BRAF or RAS gene or RET/PTC rearrangements, all of which lead to constitutive activation of the mitogen-activated protein kinase (MAPK) signaling pathway, can be found in approximately 70% of thyroid cancer patients." (PMID 31183073, 2019). "In thyroid cancer, RET has been shown to activate Ras, and thus it could indirectly lead to COX-2 activation, however, whether RET could activate COX-2 in any other way is a matter of investigation." (PMID 31142060, 2019). "In differentiated thyroid cancers, several genetic alterations such as BRAFV600E mutation, RET/PTC or PAX8/PPARγ translocation and RAS mutation are thought involved in carcinogenesis in thyroid follicular cells, and further genetic change drives stepwise dedifferentiation of cancer cells." (PMID 31666923, 2019). "Thus, in thyroid carcinoma cells, which harbor activated RET/PTC, RAS, or BRAF, CD44-ICD accumulated, a blockade of γ-secretase blunting CD44 processing." (PMID 30211160, 2018). "Interestingly, the data from Croyle et. al. also suggest that thyroid cancer cells carrying RET fusion proteins are sensitive to EGFR inhibitors." (PMID 28460442, 2017).
thyroid cancer (continued). "Likewise, aberration in RET has long been known to be involved in thyroid cancers, but the first RET fusion gene in NSCLC was found in early 2012." (PMID 28881815, 2017). "The P596L, E818K (in 2 ATCs each) and the E595K RET variation (1 ATC) have so far not been described in association with thyroid cancer or other human malignancies and their biological relevance is not known." (PMID 28489587, 2017). "DUSP6 may have a pro-tumorigenic role in thyroid carcinogenesis, as recent data demonstrated that DUSP6 silencing reduced the neoplastic properties of human thyroid carcinoma cell lines with different genetic background (RET/PTC1 and BRAFV600E)." (PMID 28910386, 2017). "Similarly GRB14 increases thyroid cancer cell growth by promoting RET signaling and its expression is correlated with human thyroid cancer invasiveness." (PMID 26788993, 2016). "We sought to test whether effects of the 14 antiproliferative hits were restricted to TPC1 or common to other thyroid cancer cell lines driven by oncogenes different from RET." (PMID 27058903, 2016). "Although there may be a tissue-specific or contextual contribution to response, our findings are similar to reported responses to RET-directed therapies in thyroid cancer and NSCLC." (PMID 26078337, 2015). "The CCDC6-RET fusion kinase in patient 1 occurred at a novel breakpoint at CCDC6 intron 2 and RET intron 10 from a chromosome 10 inversion event, which differs from the CCDC6-RET fusion kinase breakpoints in thyroid cancer and lung cancer that fused CCDC6 exon 1 to RET exon 12-20." (PMID 26078337, 2015). "Recently, molecular diagnostics has offered new techniques for detecting the most common mutations in thyroid cancer (BRAF, RAS, RET/PTC, and PAX 8/PPAR γ) in order to optimize the management of indeterminate follicular lesions and to guide the therapeutic approach more appropriately." (PMID 26693224, 2015). "However, according to IPA, exposure to ionizing radiation activates thyroid cancer signalling by rearrangements of RET and/or NTRK, both present in some of the exposed groups." (PMID 26492889, 2015). "Similarly, RET fusions, first characterized in thyroid cancer, are widely observed in lung cancers, and the EWSR1-POU5F1 fusion was detected in two rare epithelial tumors, hidradenoma of the skin and MEC of the salivary glands." (PMID 26684754, 2015). "In addition to its role in thyroid cancers, RET has been shown to functionally interact with ERα in human breast cancer cell lines." (PMID 25409876, 2014). "RET rearrangement has also been well characterized in thyroid cancer." (PMID 24744988, 2014). "In this study, we have demonstrated that SPP86 selectively inhibits this activity in a thyroid cancer cell line expressing RET/PTC1 but not in others with activating mutations in BRAF (V600E) or Ras (G13R) which lie downstream of RET." (PMID 25409876, 2014). "While activating RET mutations are associated with thyroid carcinomas and multiple endocrine neoplasias, there are no publicly available datasets that would allow us to correlate clinical outcome with the expression of Enigma and Cbl-c." (PMID 24466333, 2014). "The activators of this pathway in thyroid cancer include RET/PTC rearrangements, Ras." (PMID 24868250, 2013). "Thus, we studied these events with WRO cells, a human thyroid cancer cell line with RET/PTC rearrangement, and A549, a human lung adenocarcinoma cell line without RET/PTC." (PMID 22928011, 2012).
thyroid cancer (continued). "In conclusion, AZD1480 effectively blocks proliferation and tumor growth of activated RET- thyroid cancer cell lines, likely through direct RET inhibition in cancer cells as well as by modulation of the microenvironment (e.g. via JAK/phospho-STAT3 inhibition in endothelial cells)." (PMID 23056499, 2012). "Thus, AZD1480 should be considered as a therapeutic agent for the treatment of RET- activated thyroid cancers." (PMID 23056499, 2012). "Mutation analysis has shown that kindreds with FNMTC do not have germ line mutations in BRAF, RAS, and RET/PTC genes that are commonly mutated somatically in thyroid cancers of follicular cell origin." (PMID 21998631, 2011). "Recently, it was investigated whether sensitivity to MEK inhibition was determined by oncogene status in 13 human thyroid cancer cell lines: four with BRAF mutations, four RAS, one RET/PTC1, and four wild type." (PMID 20628483, 2010). "An open-label phase II trial with sorafenib (that inhibits a spectrum of kinases including Raf kinase, VEGFR, platelet-derived growth factor receptor, and RET tyrosine kinases) was conducted in patients with advanced, metastatic, iodine-refractory thyroid carcinoma." (PMID 20628483, 2010). "Our results support the hypothesis that thyroid cancer cells with activated BRAF are more dependent on the BRAF-ERK pathway for proliferation than those with RAS or RET/PTC1 activation." (PMID 19878585, 2009). "In addition, cases that occurred early in this Chernobyl-related thyroid cancer endemic showed a higher proportion of RET-PTC 3-positive tumours; this proportion fell and the proportion of RET-PTC 1-positive cases rose with an increasing latent period." (PMID 15150580, 2004). "Furthermore, we observed the RET variant (rs1800861, COSM4418405) in 98% of patients, reaching 100% prevalence in advanced-stage of HCC, mirroring its known associations with adamantinomatous craniopharyngioma, thyroid cancer and chronic myeloid leukemia." (PMID 41567639, 2025). "A better understanding of these issues and those that may emerge from novel clinical practices, treatments, and innovations, are necessary to provide adequate education for pathologists involved in the testing and diagnosis of RET-altered lung and thyroid cancers." (PMID 37277734, 2023). "In addition, several studies suggested that NTRK and RET gene fusion might play an important role in the occurrence and development of pediatric thyroid cancer." (PMID 38274235, 2023). "The RET/PTC fusion group had more aggressive tendencies (extrathyroidal extension, lymph node metastasis, and diffuse sclerosing variant) and was classified as intermediate risk of recurrence as per the 2015 American Thyroid Association Guidelines for Differentiated Thyroid Cancer." (PMID 37444504, 2023). "Newer and selective RET inhibitors, selpercatinib and pralsetinib, have demonstrated potent efficacy and favourable toxicity profiles in clinical trials in the treatment of RET-driven advanced thyroid cancer and are now a therapeutic option in some clinical settings." (PMID 37207147, 2023). "In addition, RET alterations play an essential role in thyroid cancer initiation and progression." (PMID 36690680, 2023). "Specifically, over half of the follicular cell-derived thyroid cancers are driven by BRAF V600E, TERT promoter mutations, and/or genetic alterations in the PI3K/AKT pathway, while the major genetic driver of MTC is germline or somatic rearranged during transfection (RET) mutations." (PMID 37081420, 2023). "Therefore, inhibiting RET activity has become a target in thyroid cancer therapy." (PMID 33419162, 2021). "It was reported that the genes, coding the MAPK/ERK and PI3K/AKT signaling cascade proteins (e.g., RET, RAS, BRAF, PI3K, PTEN, AKT), were significantly mutated in thyroid cancer, which contributed to aberrant activations of MAPK/ERK and PI3K/AKT signaling pathways of thyroid cancer." (PMID 31384179, 2019).
thyroid cancer (continued). "The initiation of thyroid cancer is often triggered by a genetic mutation in the phosphortidylinositol-3 kinase (PI3K) or mitogen-activated protein kinase (MAPK) pathway, such as RAS and BRAF, or by the rearrangement of growth factor receptor tyrosine kinase genes such as RET/PTC." (PMID 29163356, 2017). "AsuragenmiR Inform (Austin, TX, USA) mutation analysis assay and Thyroid Cancer Mutation Panel by Quest Diagnostics (Madison, NJ, USA) are the two main commercially available mutational tests which test for known genetic alterations such as BRAF, RAS, RET/PTC, and PAX8/PPARγ." (PMID 24808946, 2014). "Oncogenic PTC/RET translocations detected in thyroid cancer and cell lines are sensitive in vitro and in vivo to RET inhibitors, suggested the possibility that sunitinib, sorafinib, vandetanib, or other RET inhibitors might also be clinically effective in KIF5B/RET lung cancers." (PMID 23342255, 2012). "H&N cancers comprised 140 patients (3-4%), primarily secretory salivary carcinoma in NTRK trials (n = 12-20), thyroid carcinoma in BRAF (n = 36) and RET (n = 45) programs, and rare HER2-positive salivary duct carcinomas." (PMID 41827789, 2026). "Gene fusions involving RET, ALK, or NTRK1, among others, have been shown to correlate with metastatic potential in thyroid cancer." (PMID 41306438, 2025). "The most common RET fusions in PTC are CCDC6-RET (RET/PTC1) and NCOA4-RET (RET/PTC3), found in 90% of fusion-positive cases, whereas other follicular-derived thyroid cancers rarely harbour RET fusions." (PMID 40332222, 2025). "Further evaluation of the efficacy of selpercatinib was done in an ongoing multicenter, open-label multi-cohort trial in 41 patients with RET fusion-positive tumors beyond NSCLC and thyroid cancers." (PMID 41179283, 2025). "The relationship between the RET-PTC fusion gene and the prognosis of thyroid cancer is becoming clearer." (PMID 40584293, 2025). "Our findings support the efficacy of combined targeting of RET and EGFR in CCDC6-RET NSCLC and thyroid cancer cells, successfully preventing tumor cell growth under RET-resistant conditions." (PMID 40405293, 2025). "A subset of thyroid cancers is initiated by gene rearrangements involving receptor tyrosine kinase (RTK) genes, such as RET, ALK and NTRK (5–10%), that also activate the MAPK pathway." (PMID 41175860, 2025). "Among previously untreated patients, the ORR was higher—85% for NSCLC and 73% for RET-mutant medullary thyroid cancer (1-year PFS 92%)—while, for RET fusion-positive cancers other than NSCLC and thyroid cancer, the ORR was 43.9%." (PMID 41374970, 2025). "The recommendation was supported by results from the LIBRETTO-001 (NCT03157128) trial in patients with RET fusion-positive NSCLC, thyroid cancer, and advanced solid tumors." (PMID 41374970, 2025). "In cases of thyroid cancer, the predominant fusion events involve RET/PTC1 and RET/PTC3, which entail the fusion of the RET gene with the CCDC6 gene and the NCOA4 gene, respectively." (PMID 40586006, 2025). "In comparison, the mean TMB was 4.0 ± 1.9 for RET+ NSCLC (N = 65) and 2.6 ± 1.6 for RET+ Thyroid cancer (N = 52)." (PMID 39950716, 2025). "RET+ CRC with identified fusion partners was also found to have a significantly higher TMB when compared to RET+ NSCLC and RET+ thyroid cancer." (PMID 39950716, 2025). "In 23 patients with RET-altered solid tumors excluding NSCLC and thyroid cancer, pralsetinib achieved an ORR of 57% (95% CI: 35–77), mDOR of 11.7 months (95% CI: 5.5–19.0), mPFS of 7 months (95% CI: 5.1–13.6), and mOS of 13.6 months (95% CI: 7.5–NR)." (PMID 40576713, 2025). "Lenvatinib, a multitargeted kinase inhibitor of FGFR1–4, VEGFR1-3, KIT, RET, and PDGFR-β,4 has been proven effective for liver and thyroid cancers." (PMID 40747481, 2025). "There are several RET TKIs like selpercatinib and pralsetinib that have been approved by the U.S. Food and Drug Administration (FDA) for lung and thyroid cancers." (PMID 41374970, 2025).